CXCR4 (C-X-C motif chemokine receptor 4)
Diseases named in the same sentence as CXCR4 in open-access papers (continued):
Sharing a sentence is not in itself a finding about the gene and the disease.
cancer (continued). "We investigated the effects of curcumin, a flavonoid known for CXCL12/CXCR4 axis inhibition, on breast TME by analyzing whether it can disrupt the ADMSC-cancer positive loop." (PMID 38004606, 2023). "Here, we show that COPD alters the protein content of EVs and that HIF-1α/CXCR4 axis activation caused by COPD-EVs in non-tumorigenic epithelial cells leads to the acquisition of malignant features and cancer progression." (PMID 37838700, 2023). "Overall, these results suggest that COPD-EVs promote the increase of CD133+ cancer-initiating cells, in particular through the expansion of CD133+CXCR4+ MICs subset, along with the acquisition of pro-tumorigenic and invasive properties in HBEC-KRASV12high cells." (PMID 37838700, 2023). "For the various types of cancer featured in this review, collagen I interacts with various receptors on cancer cells (including integrinβ, Endo180 or uPARAP, DDR, LAIR-1, CXCR2 and CXCR4), opening interesting perspectives for the development of new drugs targeting such interactions." (PMID 37373151, 2023). "Additional targeted drug delivery systems based on ADCs have been marketed for the therapy of hematological neoplasms, none of which target CXCR4 cancer cells." (PMID 36986589, 2023). "Finally, CXCR4 and its ligand, CXCL12, can promote metastasis by preventing anoikis in cancer cells." (PMID 36980201, 2023). "CXCR4 is a 7-transmembrane G-protein coupled receptor (GPCR) that is highly expressed in many cell types such as lymphocytes, endothelial cells, hematopoietic stem cells, stromal fibroblasts, and cancer cells." (PMID 37497001, 2023). "Considering the selectivity of VUF11207 for CXCR7 over CXCR4, we envisioned that it may be a powerful tool to specifically measure the contribution of CXCR7 in migration and invasion of cancer cells." (PMID 37558722, 2023). "Additionally, the co-expression of transgenic CXCR4 and anti-BCMA CAR in NK cells was shown to further strengthen their cancer-eradicating effects in a MM xenograft mice model compared to CAR-NK cells without CXCR4 transfection." (PMID 36765526, 2023). "CXCL12/CXCR4 axis is also responsible for mast cells recruitment from normal vasculature or healthy tissues, which turns it into a potential target for cancer therapies." (PMID 38313431, 2023). "EMT have been shown to increase EMT induction through SDF1 secretion and binding to CXCR4 and CXCR7 in cancer cells Moreover, EMT was reported to increase in tumor-bearing obese as compared to lean mice and decrease following injection of D-CAN, a killer peptide targeting ASCs." (PMID 36766689, 2023). "Altered protein abundance of CXCR4, hyaluronan receptor CD44, or TGFβ-signaling was induced by CM in cancer cells and may contribute to phenotypical changes." (PMID 37781195, 2023). "We hypothesize that a strong correlation of CXCL12/CXCR4 and CXCL12/pCXCR4 in recurrent carcinoma will arrest migratory immune cells." (PMID 37966614, 2023). "According to the literature, high expressions of CXCR4 and SDF-1 were also detected in FTC, but mainly in the sites of distant metastases compared to primary tumors, highlighting its prognostic significance in the process of disseminating cancer cells." (PMID 36419107, 2022). "CXCR4 is highly expressed in AML, and the interactions between CXCR4 and its ligand CXCL12, constitutively secreted by BMSCs and MSCs, promote the proliferation, survival, migration, and homing of cancer cells." (PMID 35159023, 2022). "The triggering of the CXCR4/CXCL12 signaling pathway enhances trans-endothelial migration and the homing and adhesion of cancer cells in the BM niche; it also increases the expression and excretion of other disease-progressing molecules (i.e., IL-6, integrins, and growth factors)." (PMID 35566637, 2022). "Given the importance of CXCR4 as a negative prognostic factor in several cancers, our group also studied the role of the phosphorylated, activated form of CXCR4 (pCXCR4) as a prognostic factor in CRC." (PMID 35397601, 2022).
cancer (continued). "Thus, cross-linking CXCR4 by dimeric CXCL12 may elicit a “stop” signal that differs from the chemotactic signal stimulated by monomeric CXCL12 but may be similar to that elicited by the polymeric form of CXCL12 that is distributed on the surfaces of cancer cells." (PMID 35046049, 2022). "The interactions of CXCR4, HIF2A, and PPAR are documented in the literature data, proving that the HIF2A transcription regulation of CXCR4 is involved in macrophage migration and chemotaxis, as well as the PPAR-related downregulation of CXCR4 gene expression in cancer cells." (PMID 36552391, 2022). "Furthermore, it has been also demonstrated that CXCL12 and CXCR4 induce the activation of integrins which suggests a cooperation between the CXCL12–CXCR4 axis and the integrins in mediating cancer cell behavior, such as adhesion and survival." (PMID 35745762, 2022). "In response to CXCL12, CXCR4 and ACKR3 both recruit β-arrestin 2, regulating the assembly of interacting proteins that drive signaling and contribute to the functions of both receptors in cancer and multiple other diseases." (PMID 35681470, 2022). "CXCR4, its ligand CXCL12 and the atypical receptor ACKR3 are overexpressed in many human cancers." (PMID 36713377, 2022). "The invasion of cancer cells to the perivascular environment relies on their motility, in which motility-involving molecules such as ARP2/3, L1CAM, serpins, CD44, CDC42, CXCR4, epidermal growth factor receptor (EGFR), as well as Wnt7 signaling, are critical players." (PMID 36119528, 2022). "Cancer-associated fibroblasts differentiated monocytes into M2 macrophages by regulating the CXCL12/CXCR4 pathway, and then M2 macrophages could transform OSCC cells into cancer stem cell-like cells, which enhanced OSCC proliferation." (PMID 35693982, 2022). "Thus, the selective bacterial exotoxin release in CXCR4+ HNSCC cells activate caspase-3/GSDME switch from apoptosis to pyroptosis, as described for different untargeted and targeted drugs in other cancer types." (PMID 35120582, 2022). "Cancer stem cells from either human GC cell lines or tumor tissues were isolated using cell surface markers such as CD24, CD44, CD54, CD71, CD90, CD133, Lgr5, ALDH1, EpCAM, and CXCR4." (PMID 36176765, 2022). "Thus far, both CXCL12/CXCR4 and VEGF/VEGFR are the dominant pathways of EPC mobilization from bone marrow in cancer development." (PMID 35203510, 2022). "Research shows that cancer tissues contain increased levels of CXCL12 and CXCR4." (PMID 36012171, 2022). "After exposure of CXCR4+ SW1417 cells to the T22-PE24-H6 nanotoxin for a short time, at 2 or 5 hours, we found in almost all cancer cells a high overexpression of the NLRP3 protein, an inflammatory marker that initiates the signaling cascade that leads to pyroptosis." (PMID 35532120, 2022). "The subset of CD133/CXCR4/CD73+ NSCLC stem cells are endowed with immune-suppressive properties due to the release of cytokines and Ado able to activate immune cells which promote growth of cancer cells." (PMID 35563517, 2022). "Similarly, CXCL12/CXCR4 activation also increased MMP2/MMP9 and urokinase-type plasminogen activator expression by the Wnt/β-catenin pathway, enhancing cancer metastatic tendency." (PMID 36612163, 2022). "CXCR4 is the receptor for SDF-1; this member of the G-protein-coupled receptor (GPCR) family has seven transmembrane domains and plays a key role in lymph node and distant metastasis as well as cell migration in several types of cancer." (PMID 35681259, 2022). "CXCR4/CXCXL12 axis has been shown to induce the directional migration of progenitor cells in the bone marrow to the injured tissues and is involved in many biological responses, including hematopoiesis, immune response, and cancer metastasis." (PMID 35634326, 2022).
cancer (continued). "In a Univariate Hazard Cox regression analysis using the dichotomized pCXCR4/CXCR4 ratio expression in primary cancer biopsies there was no significant prediction of a better RFS (HR 0.61; 95CI 0.31 - 1.21; p = 0.161)." (PMID 35397601, 2022). "Therapies targeting CXCR4 and CCR5 have been reported as probable effective strategies for cancer." (PMID 36613922, 2022). "Double immunostaining of CXCR4/FOXP3 correlated with American Joint Committee on Cancer T-stage, independent of age or Ki67 index (P<0.01)." (PMID 35358193, 2022). "The combination of anti-CXCR4 and anti-PD-1 immunotherapy mainly focus on T cell responses but not innate anti-cancer immunity." (PMID 35615089, 2022). "Nevertheless, this study establishes a previously unknown function of CXCL12 signaling to regulate PKM2 and glucose metabolism, connecting CXCR4 and ACKR3 to the metabolic adaptations of cancer cells." (PMID 35681470, 2022). "CXCR4 activation promotes the migration of cancer cells towards CXCL12-expressing organs such as the lymph nodes, lungs, bone marrow and liver, which leads to the deposition of metastasis in these organs." (PMID 36140541, 2022). "A limitation of this study is that tasquinimod, the inhibitor for S100A9, and AMD3465, which blocks the cell surface binding of CXCL12 to CXCR4, are currently under clinical trial and has been not approved for cancer therapy yet." (PMID 35304461, 2022). "This is because autocrine overexpression of CXCL12 in some tumors may be more sensitive to CXCR4 antagonists by competing with CXCL12 for receptor binding, meaning that they may be more suitable for the application of chemokine-based anti-cancer therapies." (PMID 35743888, 2022). "Future research will determine the extent to which the CXCL12-dependent regulation of PKM2 through CXCR4 or ACKR3, either alone or in combination, controls the metabolic states of cancer cells relative to other downstream effectors, with established effects on the metabolism." (PMID 35681470, 2022). "Therefore, the correlation between CXCR4/CXCL12 expression and cancer treated with CRT has been studied by many studies." (PMID 34976180, 2022). "We hypothesized that the expression profiles of CXCL12, CXCR4, and FAPα could provide valuable information regarding cancer invasion in LARC and cancer cell survival related to nCRT resistance in LARC." (PMID 34976180, 2022). "CXCR4 (over)expression is found in multiple human cancer types, while expression is low or absent in healthy tissue." (PMID 33550492, 2022). "Non-neoplastic epithelial cells and noninvasive carcinoma cells demonstrated little plasma membrane staining of either CXCL12 or CXCR4." (PMID 34976180, 2022). "After a short summary of the recent clinical advances in CXCR4-targeted imaging and radioligand therapy (RLT) in cancer, this review will therefore particularly highlight the increasing body of evidence of the clinically relevant role of CXCR4 imaging in the context of inflammatory conditions." (PMID 34885030, 2021). "Interestingly, in the recurrent cancer biopsies of our cohort, there was a significant correlation with CD66b, IL-17, MPO, and CXCR4, suggesting a stronger immune response in samples with high CD16." (PMID 34830938, 2021). "Besides paracrine signaling, the CAF-induced IL-33 reciprocally enhanced the autocrine cancer-cell self-production of IL-33 and the corresponding CXCR4 upregulation, leading to the activation of SDF1/CXCR4 signaling subsequent to cancer progression." (PMID 34298657, 2021). "Thus, a very important step has been the discovery of EPI-X4, which as a natural CXCR4 antagonist effectively blocks CXCL12-mediated receptor internalization and suppresses the migration and invasion of cancer cells towards a CXCL12 gradient." (PMID 33669329, 2021). "The role of the CXCL12/CXCR4 axis in squamous cell carcinomas (SCC) has not been characterized to date with the same level of detail as in other types of cancer." (PMID 33530455, 2021).
cancer (continued). "However, CXCR4 also activates RAS/MAPK, PI3-kinase/AKT, and CRK signaling, which is particularly well documented in cancer cells." (PMID 34350830, 2021). "Furthermore, the expression of both CXCR4 and/or CCR7 are of significant prognostic value in multiple other cancers." (PMID 34685420, 2021). "CXCR4 knockdown Chili-Luc cells were comparatively less in number (36.5%) as compared to control cells (63.1%), suggesting that CXCR4 knockdown resulted in induction of functional DR5 on the cancer cell surface." (PMID 33966046, 2021). "Although lysosomal and proteasomal degradation of DR5 is common in cancer cells, Bafilomycin and MG-132 inhibitors failed to markedly rescue CXCR4 mediated DR5 downregulation." (PMID 33966046, 2021). "The chemokine receptor CXCR4 and prominin (CD133) expression has been found to affect the metastatic potential of RMA cells, whereas syndecan-4 and stathmin expression can predict the clinical outcome of many cancer types." (PMID 33947373, 2021). "Crosstalk between the CXCR4 and IGF axis has been documented in embryonal development and cancer." (PMID 34440844, 2021). "Since expression of CXCR2 and CXCR4 is not restricted to neutrophils, we sought to directly explore the aging process of circulating neutrophils in animal models of cancer." (PMID 34876407, 2021). "As a result, the creation of novel biased ligands for CXCR4 and PAR2 might lead to new cancer therapy options." (PMID 34943797, 2021). "Our data collectively suggests that CXCR4/STAT3/Slug axis is paramount for IR resistance of NSCLC cells, and can be regarded as a therapeutic target to enhance the IR sensitivity of this devastating cancer." (PMID 33414415, 2021). "Slug can also regulate the C-X-C Motif Chemokine Receptor 4 (CXCR4) and C-C chemokine receptor type 7 (CCR7) proteins, related to chemokines that are overexpressed in several types of cancer, including HNSCCs, and, similarly to Twist, can induce cervical lymph node metastasis." (PMID 34204259, 2021). "Consistent with the results of IL-33 in cancer cells, CXCR4 expression varied regardless of the invasion pattern grading score." (PMID 34298657, 2021). "Moreover, the increased expression of CXCR4 in situations in which TFF2 is also overexpressed, such as cancer, further supports such molecular links." (PMID 34944474, 2021). "Besides, inhibition of CXCR4, using AMD3100, in combination with PD-L1 blockade induced T-cell accumulation in a KPC mouse model leading to reduced cancer proliferation." (PMID 34646829, 2021). "While a combined inhibition of CXCR4 and CXCR7 may be advantageous for cancer treatment by more completely inhibiting CXCL12 signaling, more highly specific inhibitors may significantly reduce the side effects linked to small molecule inhibitors." (PMID 33530455, 2021). "Regarding the molecular and cellular pathways beyond such TFF2 metabolic roles, we highlight the receptor chemokine (C-X-C motif) receptor 4 (CXCR4), that belongs to the important family of G protein-coupled receptor, which is a known TFF2 receptor, including in cancer cell lines." (PMID 34944474, 2021). "HOXB9 and CSC markers were simultaneously overexpressed in human refractory PCa tissues, compared with low-grade PCa, para-carcinoma, and initial PCa tissues implying the involvement of HOXB9 signalling’s involvement in ALDH+CD44+CXCR4+CD24+-PCa cell-rendered castration resistance." (PMID 34247196, 2021). "In addition, the CXCL12/CXCR4/CXCR7 and CCL20/CCR6 chemokine axes are known to promote migration and the invasiveness of cancer." (PMID 32775427, 2020). "Therefore, CXCR4 and CXCL12 are molecular targets of interest for the development of potential targeted cancer therapies." (PMID 32410920, 2020). "Another function of this protein, which may be important for driving cancer cells in the bone marrow niche, is that CD44 can also bind CXCR4, which is crucial in retaining HSC in the niche, and might be important for cancer cells as well." (PMID 32527062, 2020).
cancer (continued). "CXCR4+ ESCC cells exhibited high expression of stemness-related genes, had higher metastatic ability, and more resistant to anti-cancer drugs, indicating that CXCR4+ cells may possess some characteristics of CSCs." (PMID 32232002, 2020). "For example, cancer chemotherapy upregulates CXCL12 and CXCR4 expression in multiple cancers." (PMID 33363463, 2020). "The niche-derived molecules regulating cancer cell dormancy include a chemokine stromal cell-derived factor 1 [SDF-1, also known as C-X-C motif chemokine ligand 12 (CXCL12)] that binds to its receptor C-X-C chemokine receptor type 4 (CXCR4) on cancer cells and anchors the cancer cells in the niche." (PMID 32232008, 2020). "Responses to either ICG-001 or DAPT did not correlate with the pathological stage or grade of the cancer or percentage of CXCR4+MET+CD44+ cells indicating that specific mechanisms of response exist." (PMID 32066735, 2020). "Many of the molecules driving homing and retention of leukemic cells in tissues have been identified; among them, the CXCL12/CXCR4 axis has been shown to be essential for hematopoietic stem cell (HSC) migration and homing and also for cancer cell migration and metastasis." (PMID 32432042, 2020). "Our results indicate that CXCR4 and its ligand CXCL12 may not only serve as prognostic indicators in BC but may also play a role in the PPI network involved in cancer progression." (PMID 32228629, 2020). "Furthermore, fucoxanthin decreased the expression of the cell surface glycoprotein CD44 and C-X-C motif chemokine receptor-4 (CXCR4), which are involved in migration, invasion, and adhesion of cancer cells to endothelial cells." (PMID 33291743, 2020). "Importantly, CXCR4 is involved in the process of directing metastatic cancer cells to organs expressing CXCL12 and also supports the growth of cancer cells in distant metastasis." (PMID 32521759, 2020). "While several studies reported successful utilization of TERT, survivin, and CXCR4 for transcriptional targeting in human cancers, none of these promoters have been investigated for their activity in canine tumors." (PMID 33166332, 2020). "The signaling by CXCR4 and CXCR7 potentiated cell motility toward SDF-1α, supporting the idea that both receptors are potential therapeutic targets for pathological conditions, such as inflammation and cancer." (PMID 33292475, 2020). "While the role of CXCR4 in regulating migration of EWS cells has been previously established, there are no data at the moment supporting the role of CD164 in modulating EWS cancer cells motility." (PMID 32719743, 2020). "In the context of CXCL12 activities in cancer, the review also addresses the roles of CXCR7 which is the other CXCL12 receptor; here, we describe the functions of CXCR7 alone or in the context of CXCR4, in regulating non-conventional cancer-related effects." (PMID 32582148, 2020). "Heparin can inhibit cancer metastasis by blocking the binding of CXCL12 and CXCR4." (PMID 32538273, 2020). "The C-X-C chemokine receptor 4 (CXCR4) is a family A G protein-coupled receptor (GPCR) that plays an important role in the immune response and in the progression of many diseases, including cancer and HIV infection." (PMID 32610042, 2020). "Similarly, this paper also exhibited high expression of CXCR4 in resistant cells and showed that its silence suppressed cisplatin resistance of TSCC, which was also consistent with that in other cancers." (PMID 32390763, 2020). "CXCR4, the receptor of the stromal cell-derived factor-1α (SDF-1α, also known as CXCL12) is one of the chemokines that has been researched extensively for its involvement in cancer metastasis and migration." (PMID 32630806, 2020). "Blocking of MM1-CM- and COM-CM-induced cancer cell invasion by both the TGFβ receptor inhibitor and CXCR4 inhibitor were also not effective." (PMID 32731484, 2020).